EFCAB13 (EF-hand calcium binding domain 13)
Synonyms: C17orf57; FLJ40342
Tractability: PROTAC: ubiquitination databases record sites on it.
Gene: Protein-coding gene on chromosome 17 (47,323,290 to 47,441,312, forward strand). Ensembl gene ENSG00000178852.
Subcellular location (Human Protein Atlas): Cytosol; Nucleoplasm; Nuclear speckles
Gene Ontology:
Cellular component: cytosol; nucleoplasm
Genetic constraint (gnomAD): Loss-of-function variants: 48 observed, 64.09 expected, observed/expected ratio (o/e) 0.75, 90% interval 0.59 to 0.95. The upper end of that interval is the gene's LOEUF score, 0.95, which puts it in group 4 of 6, group 1 being the genes least tolerant of losing a copy. Missense variants: 685 observed, 814.15 expected, observed/expected ratio (o/e) 0.84, 90% interval 0.79 to 0.9. Synonymous variants: 231 observed, 274.19 expected, observed/expected ratio (o/e) 0.84, 90% interval 0.76 to 0.94.
Homologues: Orthologues: macaque EFCAB13 (93% identical), pig EFCAB13 (57% identical), rabbit EFCAB13 (51% identical), rat Efcab3 (21% identical), mouse Efcab3 (19% identical).
Diseases named in the same sentence as EFCAB13 in open-access papers:
EFCAB13 is named in the same sentence as 4 diseases in open-access papers, as found by Europe PMC text mining. Sharing a sentence is not in itself a finding about the gene and the disease. The quoted sentences say what the papers report.
Immune System Diseases (1 paper, 2021). "The most significantly enriched GO biological process was Negative Regulation of Cell Migration (p = 5.24*10–4), whereas as of MESH terms, we found that the top three terms enriched for EFCAB13 coexpression were Immune System Diseases, Th1 Cells, and Th17 Cells, all reaching a score of 6.63." (PMID 35047017, 2021).
EFCAB13 also shares sentences with these, for which no sentence is quoted: breast carcinoma (1 paper); colon cancer (1); hypothyroidism (1).